CCND1 (cyclin D1)
Diseases named in the same sentence as CCND1 in open-access papers (continued):
Sharing a sentence is not in itself a finding about the gene and the disease.
prostate tumor (17 papers, 2006 to 2025). "From our analysis, we observed a significantly decreased relative CCND1 mRNA expression in prostate tumor tissues compared to BPH tissues." (PMID 40304827, 2025). "In this study, we revealed the expression pattern of CCND1 in prostate tumor and adjacent normal prostate tissues via using the IHC result of TMA and analyzing sequencing data." (PMID 32566661, 2020). "We co-transfected both green fluorescent protein (GFP)-Pxn and Flag-Ccnd1 into rat prostate tumour cells (R3327-5′A) and performed an IP against GFP." (PMID 27181366, 2016). "In this study, FBRA upregulated the expression of AMPK and downregulated the expression of FASN and cyclin D1 in prostate tumors." (PMID 27409632, 2016). "Additionally, we showed a significant reduction in the relative mRNA expression levels of CCND1, p15INK4b and RB in prostate tumor tissues compared to BPH tissues." (PMID 40304827, 2025). "The relative mRNA expression of CCND1, p15INK4b and RB was significantly lower in prostate tumor tissues compared to BPH tissues [CCND1: median log2(FC) value: -2.12, p = 1 × 10− 12; p15INK4b: median log2(FC) value: -0.85, p = 0.002; RB: median log2(FC) value: -1.28; p = 0.002]." (PMID 40304827, 2025). "Additionally, we observed significantly reduced mRNA expression levels of CCND1, p15INK4b, and RB in prostate tumor tissues compared to BPH tissues, while the expression levels of CDK4, CDK6, and p16INK4a remained unaltered." (PMID 40304827, 2025). "Moreover, the relative mRNA expression levels of CCND1, p15INK4b and RB were significantly lower (p<0.05) in prostate tumor tissues compared to BPH tissues." (PMID 40304827, 2025). "CCND1 (cyclinD1), a critical gene regulating cell cycle progress, recently has been reported to directly regulate the focal adhesion pathway and promote R3327 rat prostatic tumor cell migration/invasion and tumor metastasis." (PMID 30459815, 2018). "We then sought to determine whether BA can decrease the expression levels of AR and cyclin D1 proteins in TRAMP prostate tumors." (PMID 23424652, 2013). "A large number of evidences point into the same direction: FAK, and its downstream signaling molecules AKT and GSK-3β, β-catenin and its upstream and downstream signaling molecules Wnt and cyclin D1, respectively, are important players in both prostate tumor development and metastasis." (PMID 20537156, 2010). "Similarly, others have shown low cyclin D1 gene amplification (4%) in primary prostate tumours and, depending on the method of detection, 5–15% gene amplification in advanced prostate tumours." (PMID 17375037, 2007). "Of note, increased DNA damage but decreased NF-κB, cyclin D1, and c-MYC signaling activation were evident in prostate tumors with a TUBB4A defect." (PMID 35589707, 2022). "MicroRNA-302a was reported to suppress prostate tumor cell proliferation by inhibiting AKT, resulting in subsequent alterations of the AKT-GSK3β-cyclin D1 and AKT-p27 pathways." (PMID 30326936, 2018). "For example, cyclin D1 gene amplification did not increase in benign prostatic hyperplasia (BPH) or primary and refractory tumours of the prostate." (PMID 17375037, 2007).
thyroid tumor (17 papers, 2011 to 2025). A benign or malignant neoplasm affecting the thyroid gland. "A direct association has been shown between Cyclin D1 and C-myc gene expressions and the proliferation of human thyroid tumor cells." (PMID 32198408, 2020). "This association between cyclin D1 overexpression and LN metastases in thyroid neoplasm is concordant with a previous report." (PMID 30885146, 2019). "We investigated the CCND1 rs9344 (G870A) polymorphism and the expression profiles of wild-type CCND1a and shortened oncogenic isoform CCND1b at the mRNA and protein levels in 286 thyroid tumors." (PMID 30428594, 2018). "Cyclin D1 is a positive regulator of the progression from G1 to S phase and its overexpression has been reported in various carcinomas and also linked to aggressive behaviour of thyroid neoplasms." (PMID 26863116, 2016). "It has been shown that hsa-miR-195-5p can inhibit the role of cell proliferation in thyroid tumors by inhibiting cyclin D1, which is a potential therapeutic target for thyroid tumors." (PMID 39169938, 2024). "Cyclin D1 is one of the most important human oncogenes and believed to be involved in the pathogenesis and metastatic potential of thyroid tumors." (PMID 34209165, 2021). "Through ROC curve analysis, we found that the cyclin D1 immunostaining score at 5.8% identified thyroid neoplasms with a sensitivity of 94.4% and specificity of 92.3% in histological analysis (P = 0.003)." (PMID 30885146, 2019). "In this study, we determined that thyroid neoplasms showed cytological immunostaining of cyclin D1 with six independent cell clumps based on the Bethesda System." (PMID 30885146, 2019). "It has been pathologically shown that cyclin D1 (CCND1) protein is overexpressed and the protein expression levels of p21cip and p27kip were at low to rare levels in thyroid tumors, and these changes were attached to thyroid carcinogenesis." (PMID 29236027, 2017). "We found that Cyclin D1 inhibition led to a consistent reduction of cell growth in all the thyroid tumor cell lines analyzed." (PMID 26431489, 2015). "Deregulated expression of cyclin D1 is frequently an early step in neoplastic transformation in various human cancers including thyroid tumors." (PMID 23591524, 2013). "Recently, in some reports - including the study on thyroid tumours - strong correlation between Pin1 and cyclin D1 immunoexpression and/or cyclin D1 mRNA and PIN1 expression via interaction with Wnt signalling pathway has been observed." (PMID 21219594, 2011). "In immunohistochemical studies of thyroid tumours, as well as of other types of cancers (e.g., oral squamous carcinoma), high Pin1 expression promotes cyclin D1 overexpression, directly or through accumulation of beta-catenin." (PMID 21219594, 2011). "We also used LBC to investigate cyclin D1 immunolabeling in our cohort with thyroid neoplasms." (PMID 30885146, 2019). "In surgical specimens, ROC curve analysis showed a 5.8% cyclin D1 immunostaining score predicted thyroid neoplasms at 94.4% sensitivity and 92.3% specificity (P = 0.003), while a 15.7% score predicted malignancy at 86.4% sensitivity and 80.5% specificity (P < 0.0001)." (PMID 30885146, 2019). "Some studies reported that cyclin D1 overexpression significantly correlates with thyroid tumors." (PMID 30885146, 2019). "Thus, the purpose of this study was to evaluate the cyclin D1 immunostaining screening system for thyroid neoplasms as a biomarker for tumor aggressiveness." (PMID 30885146, 2019). "Overexpression of CCND1 gene was observed in both benign and malignant thyroid tumors." (PMID 28740507, 2017). "Therefore, we focused on evaluating cyclin D1 immunostaining in thyroid neoplasms." (PMID 30885146, 2019). "Studies in thyroid tumors suggest that Metformin increases p AMPK, reduces mTOR phosphorylation, downregulates S6K1/S6 signaling, and inhibits cyclin D1 and c MYC via the mTOR pathway." (PMID 41156128, 2025).
thyroid tumor (continued). "Because of the demonstrated role of cyclin D1 in PTC, we considered the potential clinical use of cyclin D1 immunostaining of preliminary samples of thyroid neoplasm." (PMID 30885146, 2019). "Interestingly, we found that silencing of Cyclin D1, MASTL and COPZ1 inhibits the growth of several further thyroid tumor cell lines." (PMID 26431489, 2015). "Further analysis of three selected hit genes, namely Cyclin D1, MASTL and COPZ1, showed that they represent common vulnerabilities for thyroid tumor cells, as their inhibition reduced the viability of several thyroid tumor cell lines, regardless the histotype or oncogenic lesion." (PMID 26431489, 2015). "To assess whether the survival genes confirmed in BCPAP cells are involved in such common pathways, we investigated the effect of CCND1, MASTL and COPZ1 gene silencing in a panel of thyroid tumor-derived cell lines representative of different tumor histotypes." (PMID 26431489, 2015). "Whether the antiproliferative effect after Cyclin D1 silencing or palbociclib treatment in thyroid tumor cells, but not in normal ones, is related to the presence of functional pRB, as reported for other tumor types, remains to be investigated." (PMID 26431489, 2015).
viral infection (16 papers, 2011 to 2025). "Other members of the network also reappeared in the gene set enrichment analysis as members of pathways associated with viral infections (DDX58, IFIT1, IRF1, MX1, STAT1) or viral carcinogenesis and cell cycle (CCND1, CCND3, CCNE1, CDC20, E2F2, RANBP1)." (PMID 30042828, 2018). "For example, CPV can trigger host G1/S cell cycle arrest via the EGFR (Y1086)/p27 and EGFR (Y1068)/STAT3/cyclin D1 axis, and in the late stage of viral infection, nuclear assembly of the progeny capsids is accompanied by virus-induced cell cycle triggering host cell G2/M phase arrest." (PMID 38384266, 2024). "Although viral infection also resulted in cyclin D1, CDK4, and CDK6 down-regulation on protein level, the level of down-regulation is not as robust as that of cyclin D3, and their protein levels could not be rescued by protease and calpain inhibitor when compared with cyclin D3." (PMID 28130444, 2017). "The results showed that as the viral infection progressed, the expression of Wnt/β-catenin pathway-related genes β-catenin, TCF-4, LEF-1, c-Myc, and Cyclin D1 were significantly upregulated in RB1B infection group." (PMID 38638910, 2024). "We also found that cyclin D1, which is a marker for the proliferation and growth of cells, decreased in Vero and MRC-5 cells in response to virus infection compared to mock-infected cells." (PMID 34835005, 2021). "4-OH-TAM also down-regulated a number of genes, including PGR, S100A8, S100A9, CCND1 and ANEXA1, which are involved in IFN α/β signaling pathway and immune/inflammatory response to viral infection." (PMID 29416786, 2018). "To monitor the efficiency of recombinant virus infection, we exposed primary bovine fetal colon cells to CSll-CMV-EGFP as well as simultaneously introduction of CSll-CMV-TERT, -cyclin D1, and -hCDK4R24C." (PMID 26624883, 2015). "Higher expression of B–cell markers CD19, CD20 in CLL with viral infection suggests a change to atypical CLL, sustained by elevated expression of known poor prognosis markers bcl–2, cyclin D1 and CD38." (PMID 22567048, 2011). "The differences in MG proliferation across groups were not due to variations in virus infection efficacy, as confirmed by measuring p27Kip1 knockdown and cyclin D1 overexpression levels by quantitative PCR." (PMID 40178080, 2025). "We found an increased value in CD38, bcl–2 and cyclin D1 markers in patients with viral infection, but unfortunately without statistical significance (p>0.05)." (PMID 22567048, 2011). "Similar to virus infection, EBNA3C gene expression increased Cyclin D1 levels without altering mRNA levels." (PMID 21347341, 2011).
cholangiocarcinoma (15 papers, 2014 to 2023). A carcinoma that arises from the intrahepatic biliary tree (intrahepatic cholangiocarcinoma) or from the junction, or adjacent to the junction, of the right and left hepatic ducts (hilar cholangiocarcinoma). "Some researchers demonstrated Tel, by inducing S‐phase and G0/G1 phase arrest and decreasing cyclin D1, inhibited cell proliferation in esophageal squamous carcinoma and cholangiocarcinoma." (PMID 35224849, 2022). "In the present study, we found that PDT treatment inhibited gemcitabine-resistant cholangiocarcinoma cells via repressing cell viability, enhancing cell apoptosis, and eliciting G1 cell cycle arrest through modulating Cyclin D1 and caspase 3 cleavage." (PMID 34805140, 2021). "Silencing of PTTG1 inhibits cell proliferation and inhibits cyclin D1 expression in cholangiocarcinoma cells." (PMID 33061798, 2020). "In fact, MSC and MSC-CM is capable of activating Wnt signaling in cholangiocarcinoma cells by promoting the nuclear translocation of β-catenin, and upregulated Wnt target genes including MMPs family, cyclin D1 and c-Myc." (PMID 28903370, 2017). "In the present study, we found that photodynamic therapy (PDT) treatment inhibited gemcitabine-resistant cholangiocarcinoma cells via repressing cell viability, enhancing cell apoptosis, and eliciting G1 cell cycle arrest through modulating Cyclin D1 and caspase 3 cleavage." (PMID 34805140, 2021). "Based on the potential importance of CcnD1 as a clinical target, and the strong anti-tumor effects of Gltn seen in preclinical models of triple-negative breast and cholangiocarcinoma, we suggest that Gltn should be considered for clinical trials as an anti-cancer agent." (PMID 24658335, 2014). "Cisplatin and oxaliplatin, the conventional anticancer chemotherapy drugs, are emphasized as a cause of well-known DAMPs’ release from cholangiocarcinoma (CCA) cells (e.g., HSP family, S100, CRT and HMGB1), whereby they trigger Akt, ERK and Cyclin-D1 to promote tumor activities." (PMID 36142453, 2022). "In cholangiocarcinoma cells, PTK7 depletion affected the level of cell-cycle related proteins, increasing Cdk2, Cdk4, Cdk6, and cyclin D1 and decreasing p16, p21, and p27, whereas it increased mitochondrial-dependent apoptosis." (PMID 25962058, 2015). "Furthermore, in vitro experiments of Gemcitabine and PDT showed that cholangiocarcinoma induces repressing cell viability, apoptosis, and eliciting of CCA in G1 phase via modulating cyclin D1 and caspase 3 cleavage." (PMID 37503319, 2023). "As a result, MYC and CCND1 are upregulated leading to CRC progression and angiogenesis.Circ-CCAC1 derived from extracellular vesicles disrupts endothelial barrier integrity when translocated onto endothelial monolayers thereby inducing angiogenesis in cholangiocarcinoma (CCA)." (PMID 37819576, 2023).
pancreatic ductal adenocarcinoma (15 papers, 2010 to 2024). An infiltrating adenocarcinoma that arises from the epithelial cells of the pancreas. "The possible reduction of YBX1 cytoplasmic availability inhibits proliferation of myeloid differentiation-inducing apoptosis and decreases the expression of cyclin D1 and cyclin E1 associated with pancreatic ductal adenocarcinoma cell growth." (PMID 36066672, 2022). "Our findings are consistent with observations made in patients with pancreatic ductal adenocarcinoma, cysts, and pancreatitis, where a progressive increase in cyclin D1 expression is observed in correlation with PanIN staging." (PMID 36077614, 2022). "Through the GSK3B/Cyclin D1/Cyclin E1 pathway, YBX1 depletion induces apoptosis and decreases cyclin D1 and cyclin E1 protein expression, resulting in a reduction in Pancreatic Ductal Adenocarcinoma growth." (PMID 36066672, 2022). "Therefore, the purpose of our study is to examine the expression of markers such as EGFR, Cyclin D1, andCDK4 in order to find a relationship with the possible long-term prognostic factors of patients affected by pancreatic ductal adenocarcinoma." (PMID 35448172, 2022). "In pancreatic ductal adenocarcinoma (PDAC), ETV4 overexpression promoted cell growth and facilitated cell cycle progression through transcriptional regulation of cyclin D1." (PMID 38849954, 2024). "The cyclin D1 (CCND1) and cyclin D3 (CCND3) are frequently co-overexpressed in pancreatic ductal adenocarcinoma (PDAC)." (PMID 20113529, 2010). "The inactivation of the tumor suppressor p16 and the overexpression of cyclin D1 (CCND1) and/or cyclin D3 (CCND3) are common in pancreatic ductal adenocarcinoma (PDAC)." (PMID 20113529, 2010).
diabetes (14 papers, 2012 to 2024). "Contrastingly, mRNAs levels of cell cycle promoters including cyclin-dependent kinase (CDK) 4, (CDK4), CDK6 and Cyclin D1 showed marked reduction during the course of diabetes." (PMID 30720765, 2019). "Although cyclin D1+/- mice were normal, life-threatening diabetes developed in 3-month-old cyclin D1+/-D2-/- mice as β-cell mass decreased after birth." (PMID 23355973, 2013). "Interestingly, stratification analyses of the association between combination genotypes of CCND1 rs1944129 and rs7177 and the risk of RCC revealed a little different in smokers status, drinking status, history of hypertension or diabetes compared with that of risk alleles." (PMID 29113352, 2017). "For example, the diabetes drug Metformin, an activator of AMPK-directed inhibition of Akt/mTOR-mediated proliferation and Cyclin D1 synthesis, reduces the incidence and progression of some cancers." (PMID 27840833, 2016). "Although cyclin D1+/− mice never developed diabetes, life-threatening diabetes developed in 3-month-old cyclin D1−/+ D2−/− mice as β-cell mass decreased after birth." (PMID 22675349, 2012). "TG shows no significant changes in Akt phosphorylation and levels of phosphoinositide 3-kinase, p85 and cyclin D1, normal islet growth and glucose homeostasis, and no protection against STZ-induced diabetes and caerulein-induced pancreatitis vs. WT." (PMID 31696115, 2019).